APOE (apolipoprotein E)
Diseases named in the same sentence as APOE in open-access papers (continued):
Sharing a sentence is not in itself a finding about the gene and the disease.
atherosclerosis (continued). "Moreover ApoE−/− mice with a heterozygous deletion of the IR and its downstream target, Insulin Receptor Substrate 1 (IRS1), also develop accelerated atherosclerosis, as well as mice lacking insulin receptor substrate 2 (IRS2−/−)." (PMID 28752048, 2017). "Similarly, ApoE-null mice lacking CD36 and SR-A were not protected against atherosclerosis development but observed a reduction in the expression of pro-inflammatory cytokines and macrophage apoptosis." (PMID 29113088, 2017). "To correct for changes related to age rather than atherosclerosis, we compared the number of CD11b+ cDC and NKT cells in ApoE−/− mice fed an atherosclerotic diet and age-matched healthy wild-type mice fed a chow diet at two time points which represent early and advanced atherosclerotic lesions." (PMID 27051078, 2016). "Specifically in ApoE-KO mice, BM-573, but not ASA, significantly decreased atherosclerotic lesions formation, showing that a dual TxAS inhibition and TP receptor antagonism is more effective in delaying atherosclerosis than single inhibition of TxA2 formation." (PMID 27019366, 2016). "Adrenalectomy stimulates atherosclerosis in LDL receptor KO mice, but not in ApoE KO mice." (PMID 28018358, 2016). "However neither apoE nor apoM were altered in CKDpatients, even in CKD5 patients with the most advanced atherosclerosis." (PMID 27600335, 2016). "In a mouse model that lacked both ApoE and CD40-TRAF6 signaling, atherosclerosis was abolished." (PMID 27146510, 2016). "Since levels of expression of MCP-1 mRNA appeared to increase with the age of the apoE−/− mice, MCP-1 may be playing a more important role in the later rather than early stages of atherosclerosis." (PMID 18560564, 2008). "In addition, plaque area was further reduced in apoE and RAGE double knockout non-diabetic mice compared with non-diabetic apoE -/- mice, confirming the protective effect of RAGE knockout on the development of atherosclerosis." (PMID 35967420, 2022). "We found that serum pyruvate in ApoE−/− mice was significantly higher than that in C57 group, but there was no statistical difference between ApoE−/−;SAP−/− and C57 mice, indicating that the SAP knockout may improve the metabolic disorder of pyruvate in the process of atherosclerosis to some extent." (PMID 36557316, 2022). "Analysis of diseased arteries from hypercholesterolemic apolipoprotein E (ApoE)−/− mice using immunofluorescent light-sheet imaging revealed that JAG1 and NOTCH4 were enriched in regions of atherosclerotic plaque compared to adjacent nonplaque areas, indicating a potential role in atherosclerosis." (PMID 36044575, 2022). "The study also revealed that genetic deletion of TRPA1 exacerbated the atherosclerotic lesion in apoE-/- mice, whereas treatment with AITC reduced the atherosclerotic lesion in apoE-/- mice but not in apoE-/-TRPA1-/- mice, suggesting its involvement in atherosclerosis development." (PMID 34912298, 2021).
atherosclerosis (continued). "On the contrary, trehalose influenced neither the progression of atherosclerosis (“cross section”: 271325.4 ± 7225.5 μm2 vs 275830.8 ± 12676.9 μm2; p > 0.05) nor the content of macrophages (CD68 staining: 45.25% ± 1.7% vs 45.52% ± 3.4%; p < 0.05) in apoE−/− mice fed an HFD." (PMID 30925684, 2019). "Hence we sought to determine whether BMT and Ang II infusion would alter atherosclerosis in BMT and non-BMT ApoE−/− mice following Ang II infusion at 0.8 mg/kg/day for 14 days." (PMID 30048944, 2018). "Moreover, aortic atherosclerotic lesion formation was similar between ApoE-/- mice and TSP1-/-ApoE-/- mice under either LF or HF feeding conditions, suggesting that TSP1may not be a major player in the development of atherosclerosis under either normal or obese conditions." (PMID 25803585, 2015). "Notably, previous work has shown that atherosclerosis increases in an animal model lacking both NPR-A and ApoE (Npr1−/− ApoE−/− mice), suggesting that lack of NPR-A could induce VSMC growth through other receptor signaling, thus enhancing the negative vascular effects due to lack of ApoE." (PMID 26720342, 2015).
Alzheimer disease (2,893 papers, 2002 to 2026). A progressive, neurodegenerative disease characterized by loss of function and death of nerve cells in several areas of the brain leading to loss of cognitive function such as memory and language. "Compared with the most common form of apoE, apoE3, the apoE4 isoform increases the risk for developing Alzheimer's disease." (PMID 41706741, 2026). "Orthodenticle homeobox 2 regulates critical period timing and neuroblast integration, whereas apolipoprotein E couples lipid metabolisms and amyloid-β homeostasis to neurogenesis with Alzheimer's disease risk." (PMID 42099804, 2026). "Apolipoprotein E4 (APOE4), a genetic risk factor of Alzheimer’s Disease, has been associated with PD-related cognitive impairment." (PMID 41557715, 2026). "In patients with Alzheimer's disease, cerebellar volume was linked to cognition in individuals with lower amyloid burden, especially in those carrying two copies of the APOE-ε4 risk gene." (PMID 42271047, 2026). "Pharmacological activation of brain Retinoid X Receptors (RXRs) enhances cognition and facilitates amyloid-beta (Aβ) clearance in Alzheimer's disease (AD) mouse models, partly by upregulating apolipoprotein E (Apoe), a major AD genetic risk factor." (PMID 41828651, 2026). "Apolipoprotein E4 (APOE4), one of the major genetic risk factors of Alzheimer’s Disease (AD), is proposed to be associated with cognitive impairment in PD." (PMID 41557715, 2026). "Apolipoprotein E receptor 2 (apoER2), a primary receptor for apoE, has recently been linked to Alzheimer's disease." (PMID 41706741, 2026). "The APOE gene, which encodes Apolipoprotein E (ApoE), is the strongest genetic risk locus for Alzheimer's disease (AD)." (PMID 41860014, 2026). "The ε4 allele of the APOE gene, encoding the E4 isoform of apolipoprotein E, is the leading genetic risk factor for late-onset Alzheimer's disease." (PMID 41768790, 2026). "We also found evidence of shared genetic liability with Alzheimer's disease via APOE, complementing recent large-scale studies in all-cause delirium." (PMID 41770756, 2026). "The likelihood of developing late-onset Alzheimer's disease (LOAD) is influenced by the specific isoforms of apolipoprotein E (ApoE), with ApoE4 being the strongest known genetic risk factor for LOAD." (PMID 41726734, 2026). "APOE’s ε4 haplotype (APOE4) is late onset Alzheimer’s disease’s (LOAD) strongest genetic risk factor." (PMID 41569459, 2026). "Apolipoprotein E ε4 (APOEε4) allele is the strongest known genetic risk factor for Alzheimer's disease (AD)." (PMID 41743467, 2026). "Large delirium genetics studies also show a strong signal at the APOE locus and support overlap between delirium risk and Alzheimer's disease-related common-variant architecture." (PMID 42199314, 2026). "Several reports demonstrated that apolipoprotein epsilon-4 allele (APOE4) expression significantly increases the genetic risk of Alzheimer's disease (AD) and chronic kidney disease." (PMID 42042624, 2026). "Metabolic dysregulation is a key feature of Alzheimer's disease (AD) pathogenesis, with the APOE ε4 variant (APOE4) representing the strongest genetic risk factor." (PMID 42164526, 2026). "The E4 allele of apolipoprotein E (APOE4) is the most extensively studied genetic risk factor for Alzheimer’s disease (AD)." (PMID 41219002, 2026). "Apolipoprotein E4 (APOE4) is the strongest genetic risk factor for Alzheimer's disease (AD), yet it's unclear how this allele promotes disease." (PMID 42100472, 2026). "The apolipoprotein E (APOE) ε4 allele represents the strongest genetic risk factor for Alzheimer's disease (AD), but its role in genetically diverse Latin American and Caribbean (LAC) populations is underexplored." (PMID 41724662, 2026). "Apolipoprotein E (APOE- gene; apoE- protein) is the strongest genetic modulator of late-onset Alzheimer’s disease (AD), with its three major isoforms conferring risk for disease ε2 < ε3 < ε4." (PMID 40275327, 2025).
Alzheimer disease (continued). "Female sex and Apolipoprotein (APOE) ε4 genotype are top risk factors for late-onset Alzheimer’s disease." (PMID 39910616, 2025). "The largest research study on disclosing the APOE genotype for the risk of ad was the Risk Evaluation and Education for Alzheimer's Disease (REVEAL) study." (PMID 41035143, 2025). "One of the well-studied genes in this context is the APOE gene, the major susceptibility gene for late-onset Alzheimer’s disease (AD), with three common alleles: APOE2, E3, and E4, which confer different levels of disease risk." (PMID 39928272, 2025). "This study presents the first comprehensive in-silico characterization of L122P and L107P ApoE variants, revealing their significant structural and binding alterations with Aβ, and their possible contribution to Alzheimer’s disease progression." (PMID 40892789, 2025). "Our study demonstrates that, despite the attenuated association between APOE ε4 and Alzheimer's disease seen in AI, APOE ε4 strongly associates with IHD in AI tribal Elders, even independently of hyperlipidemia." (PMID 41282305, 2025). "Its influence on the association between the APOE ε4 allele, cognitive function, and Alzheimer’s disease risk has been highlighted in several studies." (PMID 41226628, 2025). "The apolipoprotein E (APOE) ε4 allele is the strongest genetic risk factor for late-onset Alzheimer’s disease (AD) and cardiovascular disease." (PMID 41035826, 2025). "APOE is not only involved in Alzheimer’s disease but also associated with SCZ, as studies have demonstrated its upregulation in SCZ." (PMID 40819083, 2025). "Novel findings from genome-wide association studies have highlighted the association of Alzheimer’s disease incidence with many gene polymorphisms, apart from the Apolipoprotein-E genotype." (PMID 40710902, 2025). "The ε4 isoform of apolipoprotein E (ApoE) is the most significant genetic risk factor for Alzheimer’s disease." (PMID 40457456, 2025). "The ApoE-ε4 gene is a well-established genetic risk factor for neurodegenerative diseases, such as Alzheimer’s disease and multiple sclerosis, which are characterized by axonal demyelination in the central nervous system." (PMID 40258814, 2025). "Carrying one APOE-ɛ4 allele (heterozygote) increases the risk of developing Alzheimer's disease 3- to 4-fold, while having two APOE-ɛ4 alleles (homozygote) raises the risk by 10- to 15-fold." (PMID 40000321, 2025). "Radiation exposure has also been linked to age-dependent cognitive decline and a higher risk of neurodegenerative diseases such as Alzheimer’s disease, in a gender- and APOE isoform-dependent manner." (PMID 41289299, 2025). "Our findings extend this literature by linking MCP to Alzheimer’s disease dementia risk specifically and by exploring its interaction with APOE-ɛ4 load." (PMID 40496670, 2025). "The main associated pathological isoform of APOE in AD is the APOE-ε4 genotype; it is the highest risk factor for late-onset Alzheimer’s disease (LOAD), with the underlying mechanism of this link being both presynaptic and postsynaptic dysfunction." (PMID 40943177, 2025). "Sex and apolipoprotein E (APOE) genotype have been shown to influence the risk and progression of Alzheimer’s disease (AD)." (PMID 38867110, 2025). "APOE is the strongest risk gene for late onset Alzheimer’s disease and its expression is upregulated in microglia in response to amyloid beta." (PMID 40419479, 2025). "The main genetic risk factor for Alzheimer’s disease (AD) is the presence of the apolipoprotein E4 (APOE4) allele." (PMID 40958776, 2025). "The ε4 allele of the apolipoprotein E gene (APOE4) confers the strongest genetic risk for developing late-onset Alzheimer's disease." (PMID 40034682, 2025). "One of the major isoforms, APOE ε4 is known to be positively associated with amyloid plaques and neurofibrillary tangles formation, contributing to the pathogenesis of Alzheimer's disease." (PMID 40949174, 2025).
Alzheimer disease (continued). "Levels of neurofilament light chain, glial fibrillary acidic protein and phosphorylated-tau 181, apolipoprotein E genotype and late-onset Alzheimer’s disease polygenic risk scores were determined." (PMID 39825484, 2025). "APOE is involved in antioxidant defence mechanisms and plays an important role in Alzheimer's disease, an OS-associated disease." (PMID 39952200, 2025). "The APOE gene has been identified as the strongest genetic risk factor for late-onset Alzheimer’s disease (AD), including in recent, large-scale, genome-wide association studies (GWAS), GWAS meta-analyses, and population-based meta-analyses." (PMID 41154211, 2025). "The role of cholesterol in neurodegeneration is exemplified by APOE, the principal cholesterol transporter in the brain and the strongest genetic risk factor for Alzheimer’s disease and Lewy body dementia." (PMID 41037108, 2025). "The APOE (apolipoprotein E) locus (top SNP - rs7412, ∆Age association p-value=4.4*10–33) is associated with Alzheimer’s disease and coronary heart disease." (PMID 40497443, 2025). "Apolipoprotein E ε4 (APOE4) is the strongest genetic risk factor for late-onset Alzheimer’s disease (LOAD)." (PMID 39844286, 2025). "Genetic variation in APOE not only influences lipid homeostasis, but also modulates the risk of developing late onset Alzheimer’s disease (LOAD)." (PMID 40667248, 2025). "The Apolipoprotein E (APOE) locus was known associated with Alzheimer’s disease (AD) and cognitive decline, with a higher risk for epsilon 4 (E4) allele." (PMID 40181397, 2025). "APOE plays a critical role in the central nervous and cardiovascular systems and is a major genetic determinant of Alzheimer’s disease (AD) risk 4,5." (PMID 40631171, 2025). "A previous study validated the APOC1 SNP rs4420638 as the best proxy for APOE and the most relevant SNP in modulating Alzheimer’s disease risk." (PMID 40722932, 2025). "Exemplary, we show the estimated protein concentration for apolipoprotein E (ApoE), which is linked to cardiovascular and Alzheimer’s disease." (PMID 40157722, 2025). "A primary genetic risk factor for sporadic, late-onset Alzheimer’s disease is the ε4-type allele of the APOE gene." (PMID 40426657, 2025). "For example, in Alzheimer’s disease, genome-wide association studies (GWASs) provide more than 40 genetic loci associated with the risk of disease progression, including variability of APOE ε4 and TREM2." (PMID 40806492, 2025). "The inheritance of the ε4 allele in the APOE gene is a significant genetic risk factor associated with Alzheimer's disease." (PMID 40777747, 2025). "Alzheimer’s disease onset is correlated to carrying at least one allele of the ε4 isoform of the apolipoprotein E coding gene." (PMID 41007671, 2025). "To date, the Apolipoprotein E (APOE) ε4 allele has been widely recognised as one of the strongest genetic risk factors for Alzheimer’s disease (AD), with carriers facing a three- to four-fold increased risk of developing the disease." (PMID 41255877, 2025). "Previous studies have implicated APOE as a genetic risk factor for Alzheimer’s disease, mainly owing to its role in lipid and cholesterol transport in the brain." (PMID 41227478, 2025). "Apolipoprotein E, type ∊4 allele (ApoE4) is one of the most significant genetic risk factors of Alzheimer’s disease (AD) and is associated with both familial (early-onset) and sporadic AD." (PMID 39913635, 2025). "Apolipoprotein E gene (APOE) e4 allele is known as the strongest common genetic risk factor for Alzheimer’s disease." (PMID 41140810, 2025). "Apolipoprotein E ε4 is a major genetic risk factor for Alzheimer’s disease, and some apolipoprotein E ε4 carriers show Alzheimer’s disease–related neuropathology many years before cognitive changes are apparent." (PMID 39896129, 2025). "The opposite is true for Alzheimer disease (AD) where APOE-ε2 is protective and ε4 is a major risk factor." (PMID 40465013, 2025).